RTP2 (receptor transporter protein 2)
Description:
Specifically promotes functional cell surface expression of olfactory receptors, but not of other GPCRs.
Synonyms: Z3CXXC2; MGC78665
Tractability: Antibody: UniProt places it where antibodies can reach, with medium confidence; UniProt predicts a signal peptide or a membrane-spanning region; its Gene Ontology location is reachable by antibodies, with medium confidence.
Gene: Protein-coding gene on chromosome 3 (187,698,259 to 187,702,656, reverse strand). Ensembl gene ENSG00000198471.
Subcellular location: Cell membrane
Pathways (Reactome):
Sensory Perception: Expression and translocation of olfactory receptors
Gene Ontology:
Molecular function: olfactory receptor binding; protein binding
Biological process: protein insertion into membrane; detection of chemical stimulus involved in sensory perception of bitter taste; protein targeting to membrane
Cellular component: cell surface; plasma membrane
Genetic constraint (gnomAD): Loss-of-function variants: 16 observed, 20.57 expected, observed/expected ratio (o/e) 0.78, 90% interval 0.53 to 1.18. The upper end of that interval is the gene's LOEUF score, 1.18, which puts it in group 5 of 6, group 1 being the genes least tolerant of losing a copy. Missense variants: 327 observed, 299.84 expected, observed/expected ratio (o/e) 1.09, 90% interval 1 to 1.2. Synonymous variants: 126 observed, 116.82 expected, observed/expected ratio (o/e) 1.08, 90% interval 0.93 to 1.25.
Homologues: Orthologues: chimpanzee RTP2 (97% identical), macaque RTP2 (94% identical), pig RTP2 (88% identical), rabbit RTP2 (86% identical), guinea pig RTP2 (85% identical), mouse Rtp2 (83% identical), rat Rtp2 (82% identical), tropical clawed frog rtp3 (28% identical), tropical clawed frog rtp3 (26% identical), tropical clawed frog rtp3a.3 (22% identical), tropical clawed frog rtp3d (20% identical). Paralogues in human: RTP1 (82% identical), RTP3 (30% identical), RTP4 (28% identical), RTP5 (25% identical).
Diseases named in the same sentence as RTP2 in open-access papers:
RTP2 is named in the same sentence as 1 disease in open-access papers, as found by Europe PMC text mining. Sharing a sentence is not in itself a finding about the gene and the disease. The quoted sentences say what the papers report.
infection (2 papers, 2020 to 2025). The state of being infected such as from the introduction of a foreign agent such as serum, vaccine, antigenic substance or organism. "To test this possibility, we isolated six such phage clones and measured their infection efficiency on rtp2-expressing cells." (PMID 41091762, 2025).